GNL3L (G protein nucleolar 3 like)
Description:
Stabilizes TERF1 telomeric association by preventing TERF1 recruitment by PML. Stabilizes TERF1 protein by preventing its ubiquitination and hence proteasomal degradation. Does so by interfering with TERF1-binding to FBXO4 E3 ubiquitin-protein ligase. Required for cell proliferation. By stabilizing TRF1 protein during mitosis, promotes metaphase-to-anaphase transition. Stabilizes MDM2 protein by preventing its ubiquitination, and hence proteasomal degradation. Required for normal processing of ribosomal pre-rRNA. Binds GTP.
Synonyms: FLJ10613; GNL3B
Tractability: PROTAC: UniProt records ubiquitination sites on it; ubiquitination databases record sites on it; its protein half-life has been measured.
Gene: Protein-coding gene on chromosome X (54,529,900 to 54,621,565, forward strand). Ensembl gene ENSG00000130119.
Subcellular location: Nucleus, nucleolus
Subcellular location (Human Protein Atlas): Nucleoli; Cytosol; Nucleoplasm
Gene Ontology:
Molecular function: protein binding; RNA binding; GTP binding
Biological process: negative regulation of protein sumoylation; negative regulation of protein ubiquitination; negative regulation of telomere maintenance via telomerase; positive regulation of protein localization to chromosome, telomeric region; positive regulation of protein-containing complex assembly; regulation of protein stability
Cellular component: membrane; nucleolus; telomerase holoenzyme complex
Homologues: Orthologues: chimpanzee GNL3L (99% identical), macaque GNL3L (97% identical), pig GNL3L (92% identical), dog GNL3L (91% identical), rabbit GNL3L (88% identical), rat Gnl3l (88% identical), mouse Gnl3l (87% identical), guinea pig GNL3L (84% identical), tropical clawed frog gnl3l (51% identical), zebrafish gnl3l (47% identical), Drosophila melanogaster CG10914 (11% identical), Caenorhabditis elegans noa-1 (10% identical). Paralogues in human: GNL3 (30% identical), GNL2 (24% identical), LSG1 (20% identical), GNL1 (17% identical), MTG1 (14% identical), NOA1 (12% identical).
Diseases named in the same sentence as GNL3L in open-access papers:
GNL3L is named in the same sentence as 39 diseases in open-access papers, as found by Europe PMC text mining. Sharing a sentence is not in itself a finding about the gene and the disease. The quoted sentences say what the papers report.
colon cancer (3 papers, 2020 to 2025). "Other researchers have found that miR‐4454 is a key precursor of the post‐transcriptional inhibition of the GNL3L gene in colon cancer progression, and silencing GNL3L significantly reduced the survival of colon cancer cells." (PMID 40856423, 2025). "To investigate the important role of GNL3L in colon cancer cells, we employed the Ambion® predesigned siRNA to silence endogenous GNL3L in the LoVo colon cancer cells." (PMID 32422901, 2020). "Cell proliferation assays showed that the depletion of GNL3L remarkably suppressed LoVo colon cancer proliferation, by ~40% at different time points." (PMID 32422901, 2020). "The findings of previous studies on the relationship between GNL3L and NF-κB promoter assays and that of our studies on colon cancer were consistent in that the depletion of GNL3L remarkably reduced the luciferase signals." (PMID 32422901, 2020). "Furthermore, we confirmed the GNL3L silencing in the microsatellite stable metastatic SW620 colon cancer cell line using shRNA." (PMID 32422901, 2020). "We further examined the functional effect of GNL3L in colon cancer cells in vivo by subcutaneously injecting LoVo cells pretreated with a predesigned GNL3L silencer that is activated in vivo, and the systemic delivery of predesigned siRNA was performed thrice with one-week intervals." (PMID 32422901, 2020). "Notably, we found that miR-4454 was downregulated in chemoresistant CRC and that one of the target genes, GNL3L, had a higher expression level in the CPT-11-R cell line compared to that in the LoVo colon cancer parental cell line." (PMID 32422901, 2020).
colorectal cancer (3 papers, 2020 to 2023). A primary or metastatic malignant neoplasm that affects the colon or rectum. "In contrast, in colorectal cancer, the overexpression of miR-4454 reduced the survival of cancer cells dependent on GNL3L/NF-kB signal, supporting its role as a tumor suppressor." (PMID 37510314, 2023).
acute myeloid leukemia (2 papers, 2022 to 2024). Acute myeloid leukemia (AML) is a group of neoplasms arising from precursor cells committed to the myeloid cell-line differentiation. "The GEPIA database analysis results show that GNL3L is highly expressed in DLBC (diffuse large B-cell lymphoma), LAML (acute myeloid leukemia), LGG (low-grade glioma of the brain), and TGCT (testicular cancer) tumor tissues." (PMID 36230520, 2022).
breast carcinoma (2 papers, 2015 to 2022). "According to research, GNL3L plays a significant role in many cancers, such as renal cancer, colorectal cancer, esophageal cancer, liver and rectal cancer, and breast cancer." (PMID 36230520, 2022).
esophageal cancer (2 papers, 2022 to 2024). A primary or metastatic malignant neoplasm involving the esophagus. "From the results of the overexpression and knockdown studies, authors suggested that GNL3L acts in particular on the proliferation of esophageal cancer cells." (PMID 39519555, 2024). "By means of transient transfection technology, we increased or decreased the expression of the GNL3L gene in two esophageal cancer cells (KYSE30 and KYSE150) and performed clone formation assays, respectively." (PMID 36230520, 2022). "At the same time, we established an esophageal cancer (ESCA) prediction model with strong predictive ability and proved that GNL3L can significantly affect the proliferation ability of esophageal cancer cells through clone formation assays." (PMID 36230520, 2022). "From the results of the overexpression and knockdown experiments, it can be seen that GNL3L significantly affects the proliferation ability of esophageal cancer cells." (PMID 36230520, 2022). "From the results of overexpression and knockdown experiments, it can be seen that GNL3L significantly affects the proliferation ability of esophageal cancer cells." (PMID 36230520, 2022). "Finally, in order to further study the effect of GNL3L expression on esophageal cancer, we supplemented a biological experiment and performed a clone formation assay of GNL3L." (PMID 36230520, 2022). "The results of two clone formation assays showed that the clone formation ability of esophageal cancer cells was significantly increased after the high expression of GNL3L, and the clone formation ability of esophageal cancer cells was significantly reduced after the low expression of GNL3L." (PMID 36230520, 2022). "The established ESCA prediction model had a strong predictive ability, and GNL3L could significantly affect the proliferation of esophageal cancer cells." (PMID 36230520, 2022). "Furthermore, it can be seen that GNL3L significantly affects the proliferation ability of esophageal cancer cells." (PMID 36230520, 2022). "Finally, an esophageal cancer (ESCA) prediction model was established, and GNL3L clone formation assays were performed." (PMID 36230520, 2022).
lymph node metastases (2 papers, 2017 to 2025). "The results showed that high expression of GNL3L was significantly associated with lymph node metastasis in ESCC patients (p = 0.011) and distant metastasis (p = 0.008)." (PMID 40856423, 2025).
esophageal squamous cell carcinoma (1 paper, 2025). Esophageal squamous cell carcinoma (ESCC) is a type of esophageal carcinoma (EC) that can affect any part of the esophagus, but is usually located in the upper or middle third. "Association between GNL3L expression and clinicopathological characteristics in esophageal squamous cell carcinoma (ESCC) patients." (PMID 40856423, 2025).
metastatic cancer (1 paper, 2020). A carcinoma which has spread from the original site of growth to another anatomic site. "The results demonstrated that the low expression of GNL3L in adjacent normal patient tissue was significantly and inversely correlated with the high expression of GNL3L in cancer and metastatic cancer patient tissues." (PMID 32422901, 2020).
metastatic tumor (1 paper, 2020). "We performed IHC experiments to evaluate GNL3L expression using a commercial human CRC (with respective metastatic tumor and adjacent normal cells) tissue array (CO992a)." (PMID 32422901, 2020).
Pancytopenia (1 paper, 2022). An abnormal reduction in numbers of all blood cell types (red blood cells, white blood cells, and platelets). "In this context, we analyzed the prognostic and immunological value of GNL3L in pancytopenia." (PMID 36230520, 2022).
renal clear cell carcinoma (1 paper, 2022). "However, the GNL3L gene was found in KIHC (hepatocellular liver cancer), KIRC (renal clear cell carcinoma), KIRP (renal papillary cell carcinoma), SKCM (skin melanoma), and THCA (thyroid cancer)." (PMID 36230520, 2022).
cancer (8 papers, 2017 to 2025). A tumor composed of atypical neoplastic, often pleomorphic cells that invade other tissues. "GNL3L has been associated with tumor mutation burden and microsatellite instability in various cancers." (PMID 40856423, 2025). "The results indicated that GNL3L is genetically altered in a variety of cancers, and the types of variation are mainly mutations, structural variants, and deep deletions." (PMID 36230520, 2022). "A mechanism underlying miR-4454-mediated sensitization of cancer cells involves the downregulation of guanine nucleotide-binding protein-like 3-like protein (GNL3L), an activator of NF-κB transcription activity." (PMID 33066509, 2020). "Later, we found that GNL3L is a missense mutation in most cancers." (PMID 36230520, 2022). "The results of this study show that the expression of GNL3L is associated with TMB and MSI in various cancers, so the high expression of GNL3L may affect the treatment of immune checkpoint inhibitors." (PMID 36230520, 2022). "The results suggested that GNL3L is associated with both molecular subtypes and clinical stages in most cancers and may play a role in cancer growth and progression." (PMID 36230520, 2022). "Meanwhile, in order to further analyze the prognostic value and clinical value of GNL3L in cancer, we constructed a multivariate Cox-based risk nomogram for predicting the survival probability of ESCA patients, and we found that the model has a good predictive ability." (PMID 36230520, 2022). "The final results showed that GNL3L is differentially expressed in the vast majority of cancers, is associated with the prognosis of various cancers, and may affect cancer occurrence through processes such as ribonucleoprotein, ribosomal RNA processing, and cell proliferation." (PMID 36230520, 2022). "The data reported also highlight the role of GNL3L in terms of clinical value and prognosis, supporting its role as a novel pan-cancer biomarker." (PMID 39519555, 2024). "In this study, we analyzed the expression, prognosis, and immune roles of GNL3L in pan-cancer from multiple omics analyses." (PMID 36230520, 2022). "Second, this study only studied data analyses of GNL3L and various cancers and only performed a biological experiment with a clone formation assay." (PMID 36230520, 2022). "Univariate OS, PFI, and DSS analysis of 33 cancer types showed that GNL3L has different prognostic values in different cancer types." (PMID 36230520, 2022). "The relationship between GNL3L expression and molecular subtypes and clinical stages in cancer was discussed next, leading to a study of the potential mechanisms of action." (PMID 36230520, 2022). "GNL3L was shown to be negatively correlated with T cell CD8 in the majority of cancers; however, it is positively correlated in UVM (Spearman r = 0.23, p = 0.045)." (PMID 36230520, 2022). "GNL3L is negatively correlated with the CD56 dim natural killer cell in the majority of cancers; however, a positive correlation was discovered in ESCA (Spearman r = 0.212, p = 0.0087)." (PMID 36230520, 2022). "Next, in immunoassays, GNL3L was found to be significantly associated with TMB, MSI, MMR, and various immune cells in various cancers." (PMID 36230520, 2022). "After determining the prognostic value of GNL3L, the association between GNL3L and TMB, MSI, and MMR in 33 cancers was discussed." (PMID 36230520, 2022). "Then, the analysis results of OS, PFI, and DSS showed that GNL3L has different prognostic values in different cancers." (PMID 36230520, 2022). "Univariate OS, PFI, and DSS analysis of data from 33 cancer types showed that GNL3L has different prognostic values in dissimilar types of cancer." (PMID 36230520, 2022). "These new findings represent a significant advance in defining the major role of GNL3L in the immune microenvironment and cancer analysis." (PMID 36230520, 2022). "In the present study, the relevance of GNL3L expression in the prognostic value of cancer was also analyzed." (PMID 36230520, 2022).
cancer (continued). "This indicates that GNL3L is differentially expressed in the majority of cancers and is a potential biomarker." (PMID 36230520, 2022). "More biological experimental work is needed to determine the precise function of GNL3L in cancer occurrence and prognosis." (PMID 36230520, 2022). "Firstly, the expression and prognostic value of GNL3L in pan-cancer were discussed using the TIMER2 database, the GEPIA database, the cBioportal database, COX regression analysis, and enrichment analysis." (PMID 36230520, 2022). "Other researchers found that GNL3L plays an important role in a variety of cancers and plays an important role in cell proliferation and ribosome synthesis." (PMID 36230520, 2022). "In conclusion, we analyzed the expression characteristics, enrichment value, and prognostic value of GNL3L in pan-cancer and established an ESCA prediction model." (PMID 36230520, 2022). "In conclusion, the results of the GNL3L expression analysis showed that the GNL3L gene is differentially expressed in the vast majority of cancers and correlated with molecular subtypes and clinical stages." (PMID 36230520, 2022). "The final results showed that GNL3L is differentially expressed in a variety of cancers, plays a prognostic role, and has good immune value." (PMID 36230520, 2022). "The results of this study indicated that GNL3L is highly expressed in a variety of cancers, has good prognostic and immune value, and is a potential prognostic immune biomarker." (PMID 36230520, 2022). "This study aimed to investigate the expression, prognosis, and immune value of GNL3L in pan-cancer from multiple omics analyses." (PMID 36230520, 2022). "Meanwhile, in this study, we found that GNL3L expression is significantly correlated with the prognosis and immune cell infiltration of various cancers, such as ESCA, KIRC, LGG, and SARC." (PMID 36230520, 2022). "GNL3L is negatively correlated with T cell regulation (Tregs) in the majority of cancers; however, a positive correlation was found in ESCA (Spearman r = 0.25, p = 0.001) and LAML (Spearman r = 0.17, p = 0.043)." (PMID 36230520, 2022). "GNL3L overexpression was positively correlated with the progression of cancer and metastasis as determined using protein expression measures in human CRC tissue array samples." (PMID 32422901, 2020). "Given that there is an inverse relationship between the normal and cancer tissue expression of GNL3L, it is interesting to evaluate their expression patterns in clinical samples." (PMID 32422901, 2020). "By our analyses, in patients with cancer anorexia, we also observed a hypomethylation of GNL3L." (PMID 39519555, 2024). "Therefore, in this study, the method of multi-omics analysis was used to study GNL3L in pan-cancer from multiple perspectives." (PMID 36230520, 2022). "Through GO analysis results and the cellular localization and functions of GNL3L, it can be seen that GNL3L may affect the occurrence of cancer through ribosomal RNA processing." (PMID 36230520, 2022). "We also found that GNL3L is positively correlated with Type 2 T helper cells in the majority of cancers; however, it is negatively correlated in TGCT (Spearman r = −0.182, p = 0.026), COAD (Spearman r = −0.304, p = 3.45 × 10−11), and READ (Spearman r = −0.21, p = 0.0075)." (PMID 36230520, 2022). "GNL3L protein expression is significantly higher in various cancers than in normal tissues." (PMID 36230520, 2022). "In most cancer types, there are remarkable dissimilarities in GNL3L expressions in different immune subtypes, which may demonstrate that GNL3L is a novel immune-related biomarker." (PMID 36230520, 2022). "This also showed that GNL3L is negatively correlated with CD56 bright natural killer cells in the majority of cancers, especially MESO (Spearman r = −0.394, p = 0.00027), SARC (Spearman r = −0.476, p = 4.44 × 10−16), and ESCA (Spearman r = −0.380, p = 1.32 × 10−6)." (PMID 36230520, 2022). "Therefore, GNL3L can serve as a potential pan-cancer biomarker." (PMID 36230520, 2022).
cancer (continued). "Moreover, GNL3L may affect the occurrence of cancer through processes such as ribonucleoprotein, ribosomal RNA processing, and cell proliferation." (PMID 36230520, 2022). "In cancer conditions, LDOC1 expression is downregulated and GNL3L ultimately enhances NF-κB activity by regulating phosphorylation levels and stability of the NF-κB p65 subunit and IκB." (PMID 39682774, 2024). "Then, GNL3L protein expression levels were investigated using the UALCAN database and HPA database, and immunohistochemical images in various cancers were studied." (PMID 36230520, 2022). "The heatmap results showed that GNL3L was only positively correlated with PMS2 in UCS, which co-expressed and significantly correlated with at least two of these genes in the remaining cancers." (PMID 36230520, 2022). "Moreover, targeted bisulfite NGS methodology validated microarray data on four selected genes (GNL3L, FHL1, FLNA, and PGRMC1), confirming that they were hypomethylated in patients with cancer anorexia in comparison with controls." (PMID 39519555, 2024). "Thus, it was demonstrated that GNL3L expression correlates with relatively linear copy number values and affects CNA in a variety of cancers." (PMID 36230520, 2022). "There has been evidence that microRNAs could modulate drug-resistant genes, thereby playing important roles in chemosensitivity, and the GNL3L gene can be affected by LDOC1, but this gene is mostly hypermethylated in cancers." (PMID 32422901, 2020). "However, a comprehensive analysis of GNL3L expression, prognosis, and immunity on the pan-cancer level has not yet emerged." (PMID 36230520, 2022).